EIF1 (eukaryotic translation initiation factor 1)
Description:
Component of the 43S pre-initiation complex (43S PIC), which binds to the mRNA cap-proximal region, scans mRNA 5'-untranslated region, and locates the initiation codon. Together with eIF1A (EIF1AX), EIF1 facilitates scanning and is essential for start codon recognition on the basis of AUG nucleotide context and location relative to the 5'-cap. Participates to initiation codon selection by influencing the conformation of the 40S ribosomal subunit and the positions of bound mRNA and initiator tRNA; this is possible after its binding to the interface surface of the platform of the 40S ribosomal subunit close to the P-site. Together with eIF1A (EIF1AX), also regulates the opening and closing of the mRNA binding channel, which ensures mRNA recruitment, scanning and the fidelity of initiation codon selection. Continuously monitors and protects against premature and partial base-pairing of codons in the 5'-UTR with the anticodon of initiator tRNA. Together with eIF1A (EIF1AX), acts for ribosomal scanning, promotion of the assembly of 48S complex at the initiation codon (43S PIC becomes 48S PIC after the start codon is reached), and dissociation of aberrant complexes. Interacts with EIF4G1, which in a mutual exclusive interaction associates either with EIF1 or with EIF4E on a common binding site. EIF4G1-EIF1 complex promotes ribosome scanning (on both short and long 5'UTR), leaky scanning (on short 5'UTR) which is the bypass of the initial start codon, and discrimination against cap-proximal AUG. Is probably maintained within the 43S PIC in open conformation thanks to eIF1A-EIF5 interaction. Once the correct start codon is reached, EIF1 is physically excluded from the decoding site, shifting the PIC into the closed conformation and arresting it at the start codon.
Synonyms: SUI1; EIF-1; ISO1; A121; EIF1A
Tractability: Small molecule: a structure with a bound ligand is known. PROTAC: ubiquitination databases record sites on it; its protein half-life has been measured.
Gene: Protein-coding gene on chromosome 17 (41,688,883 to 41,692,668, forward strand). Ensembl gene ENSG00000173812.
Subcellular location: Cytoplasm
Gene Ontology:
Molecular function: protein binding; ribosomal small subunit binding; RNA binding; translation initiation factor activity; translation factor activity, RNA binding
Biological process: regulation of translational initiation; translational initiation; regulation of gene expression
Cellular component: cytoplasm; eukaryotic 43S preinitiation complex; eukaryotic 48S preinitiation complex; multi-eIF complex; nucleus
Genetic constraint (gnomAD): Loss-of-function variants: 3 observed, 12.38 expected, observed/expected ratio (o/e) 0.24, 90% interval 0.11 to 0.63. The upper end of that interval is the gene's LOEUF score, 0.63, which puts it in group 2 of 6, group 1 being the genes least tolerant of losing a copy. Missense variants: 64 observed, 143.33 expected, observed/expected ratio (o/e) 0.45, 90% interval 0.36 to 0.55. Synonymous variants: 67 observed, 53.41 expected, observed/expected ratio (o/e) 1.25, 90% interval 1.03 to 1.54.
Homologues: Orthologues: chimpanzee EIF1 (100% identical), dog EIF1 (100% identical), guinea pig EIF1 (100% identical), pig EIF1 (100% identical), mouse Eif1 (99% identical), zebrafish eif1 (92% identical), tropical clawed frog eif1 (87% identical), Drosophila melanogaster eIF1 (70% identical). Paralogues in human: EIF1B (92% identical).
Diseases named in the same sentence as EIF1 in open-access papers:
EIF1 is named in the same sentence as 22 diseases in open-access papers, as found by Europe PMC text mining. Sharing a sentence is not in itself a finding about the gene and the disease. The quoted sentences say what the papers report.
Arthritis (1 paper, 2022). Inflammation of a joint. "Opposite and distinct transcript expression with a higher expression in NP compared to iAF was observed for genes associated with initiation of mRNA translation (EIF1), cell-cycle progression (RGCC) and pathophysiology of arthritis (LGALS1)." (PMID 35409356, 2022).
breast cancer (1 paper, 2020). A primary or metastatic malignant neoplasm involving the breast. "In breast cancer, about 2.4% and 0.9% of cases were reported to have genomic alterations for eif1 or eif1ax, respectively." (PMID 32708122, 2020).
colon carcinoma (1 paper, 2017). "In situ detection confirmed an overexpression at the mRNA level of eIF1 and eIF5 in colon carcinoma vs. NNT (p<0.001 and p<0.05)." (PMID 29254159, 2017).
cyst (1 paper, 2024). A sac-like closed membranous structure that may be empty or contain fluid or amorphous material. "In contrast, most cyst-forming apicomplexans have two paralogs of eIF1, implying that one of these eIF1 paralogs may have evolved to regulate protein synthesis to facilitate cyst formation." (PMID 38782906, 2024).
diabetes (1 paper, 2025). "Our discovery of increased expression of EIF1 transcripts in two donors with MS treated with metformin for diabetes, compared to similar MS donors without metformin treatment, at least suggests similarities in adult human brains." (PMID 40885740, 2025).
diabetic retinopathy (1 paper, 2022). "Among PPARα-bound genes, EIF1 is one of the overlapped genes with pemafibrate-induced genes; pemafibrate-treated HUVECs showed a reduced inflammatory reaction and protective effects against diabetic retinopathy." (PMID 35308095, 2022).
epilepsy (1 paper, 2015). A brain disorder characterized by episodes of abnormally increased neuronal discharge resulting in transient episodes of sensory or motor neurological dysfunction, or psychic dysfunction. "The high-hubs in community C are either involved in mechanisms related to epilepsy pathogenesis (DFF40 and PTPRZ1) or in the control of gene expression and translation initiation (LARP4, EIF1)." (PMID 26011637, 2015).
gastric cancer (1 paper, 2025). A primary or metastatic malignant neoplasm involving the stomach. "Key findings include the identification of EIF1 and RPS12 as critical genes with causal links to gastric cancer progression, significantly influencing immune infiltration and key signaling pathways such as oxidative phosphorylation and ribosome biogenesis." (PMID 41261408, 2025).
glioma (1 paper, 2019). A benign or malignant brain and spinal cord tumor that arises from glial cells (astrocytes, oligodendrocytes, ependymal cells). "The fact that eIF1AD but not eIF1 or eIF1A, is abnormally expressed in gliomas should encourage studies aiming at elucidating its function, in particular in gliomas." (PMID 31795417, 2019).
hepatocellular carcinoma (1 paper, 2022). A malignant tumor that arises from hepatocytes. "eIF1 was found to be increased a series of disease risks, such as aneurysmal bone cyst, Parkinson’s disease, hepatocellular carcinoma (HCC), breast cancer and ductal adenocarcinoma." (PMID 36387239, 2022).
liver cancer (1 paper, 2025). An epithelial or non-epithelial malignant neoplasm that arises from the liver. "For instance, analyzing public datasets of cancers such as pancreatic, lung, and liver cancers may reveal the potential of EIF1 and RPS12 as broad-spectrum anti-tumor targets." (PMID 41261408, 2025).
ovarian carcinoma (1 paper, 2023). A malignant neoplasm originating from the surface ovarian epithelium. "A comparison of endothelial cells between healthy ovarian and ovarian cancer tissues revealed that genes such as RACK1, S100A6, and C1orf186 were significantly upregulated, while GMB2L1, TM4SF1, and EIF1 were significantly downregulated in the ovarian cancer samples." (PMID 37124501, 2023).
Sepsis (1 paper, 2020). Sepsis is defined as life-threatening organ dysfunction caused by a dysregulated host response to infection. "In a gram-negative animal sepsis model, the EIF1/EIF2a transcription regulators were mediators of translation initiation block in late-phase sepsis when transcriptomic changes were examined at multiple time points." (PMID 32154187, 2020).
thyroid cancer (1 paper, 2025). "Analysis of single-cell sequencing data revealed that BRAF, EIF1 AX, KRAS, PIK3 CA, and TERT are significantly up-regulated in various immune cells within thyroid cancer, underscoring their potential regulatory roles in the immune microenvironment." (PMID 40450370, 2025). "The results revealed significant increases in the expression of BRAF, EIF1 AX, KRAS, PIK3 CA, and TERT genes across all types of immune cells in thyroid cancer, indicating their variability and potential regulatory roles in the immune microenvironment." (PMID 40450370, 2025).
cancer (7 papers, 2014 to 2025). A tumor composed of atypical neoplastic, often pleomorphic cells that invade other tissues. "Such cross-cancer investigations can expand the applicability of EIF1 and RPS12 and offer a comprehensive understanding of the general mechanisms of NETs in tumor progression." (PMID 41261408, 2025). "The eIF1-eIF4G1 complex has been targeted using small-molecule inhibitors, i.e., i14G1-10 and i14G1-12, which are effective in killing multiple cancer cell lines." (PMID 39409166, 2024). "The induced expression of eIF1 is detected in various human cancer cell lines treated with UV or base damaging agents." (PMID 33148274, 2020). "However, to successfully implement these compounds as anti-cancer therapeutics, further development of these eIF1-eIF4G1 complex inhibitors, i.e., i14G1s, is required." (PMID 39409166, 2024). "EIF1 also shows a significant difference in expression between AC and all other types The dysregulation, specifically the overexpression of the initiation factors, has been reported previously to occur frequently in cancer." (PMID 35681609, 2022). "Therefore, targeting these translation factors alone or in their interactive complexes provides a platform to block the expression of mRNAs highly dependent on mRNA scanning, suggesting potentially improved cancer therapies for cancer involving upregulation or dependencies on eIF1 and eIF1A." (PMID 39409166, 2024). "Mechanistically, EIF1 and RPS12 are central regulators of ribosome biogenesis and translational initiation, processes that are frequently upregulated in cancer cells." (PMID 41261408, 2025). "EIF1 and RPS12 emerge as promising candidates for precision medicine, with broader implications for NET-related cancer research." (PMID 41261408, 2025). "Screening these candidate miRNAs for expression correlation in HNSCC via the Pan-cancer subproject of the ENCORI database revealed significant negative correlations in 13 EIF1-miRNAs, 21 LARP1-miRNAs, and 1 METTL1-miRNA interactions." (PMID 40018039, 2025).
tumor (6 papers, 2016 to 2025). "EIF1 plays a crucial role in protein synthesis initiation, with gene mutations potentially linked to specific tumor risks." (PMID 40018039, 2025). "This asRNA is located in the locus containing genes JUP, FKBP10, HAP1, LEPREL4 and EIF1 upregulated in HPV16+ tumours." (PMID 29263803, 2016). "Importantly, our MR analysis validated the causal relationships between EIF1 and RPS12 and GC development, providing robust genetic evidence for their involvement in tumor biology." (PMID 41261408, 2025). "In future studies, we plan to investigate the synergistic effect of LARP1 with other known prognostic molecules (such as EIF3D, EIF1, METTL1) in HNSCC, particularly their potential interactions in tumor cell growth, metastasis, and immune evasion." (PMID 40018039, 2025). "The eukaryotic translation initiation factors, namely, EIF1, EIF3E, EIF3H, EIF4G2, EIF5, and EIF6, were all upregulated in the brain metastasis-derived tumor cells." (PMID 33170151, 2020). "Additionally, quantitative immunohistochemical analysis revealed that the expression of EIF3D, EIF1, LARP1, and METTL1 in the tumor group was significantly higher than in adjacent tissues." (PMID 40018039, 2025). "In this context, EIF1 and RPS12 may serve as molecular hubs connecting metabolic and translational machinery with immune regulation, ultimately promoting a tumor-permissive microenvironment." (PMID 41261408, 2025).
infection (3 papers, 2014 to 2025). The state of being infected such as from the introduction of a foreign agent such as serum, vaccine, antigenic substance or organism. "Levels of CXADR, BNIP3, and SPARCL1 mRNA were measured during the persistent phase of infection with Ad5dl309 (56–77 days p.i.)and normalized to the housekeeping gene EIF1." (PMID 41497616, 2025). "Quantities of viral transcripts from persistently-infected BJAB and KE37 cells were determined relative to a cellular housekeeping gene EIF1 (which was not altered by infection, data not shown)." (PMID 31864392, 2019).
EIF1 also shares sentences with these, for which no sentence is quoted: viral infection (2 papers); Alzheimer disease (1); Hashimoto thyroiditis (1); pancreatic tumor (1); rectum cancer (1).